GREM1 (gremlin 1, DAN family BMP antagonist)
Diseases named in the same sentence as GREM1 in open-access papers (continued):
Sharing a sentence is not in itself a finding about the gene and the disease.
tumor (continued). "Thus, we have established the monumental impact of these macrophages in the immuno-suppresive, pro-fibrotic niche, which we hypothesize may help support the role of CTHRC1+GREM1+ myCAF and tumor cells further through EMT and other pro-tumor mechanisms." (PMID 39075108, 2024). "A higher protein level of GREM1 in PDAC correlated with stroma formation and immunosuppression by recruiting varieties of immunosuppressive cells, including T regulatory cells (Tregs), M2 macrophages, myeloid-derived suppressor cells (MDSCs), and exhaustion T cells into the tumor microenvironment." (PMID 36091126, 2022). "Moreover, combination treatment showed downregulation of the expression of inflammation-related genes that are involved in tumor inflammation, such as Gremlin (GREM1), IL-1β, IL-4, NF-κB, and prostaglandin-endoperoxide synthase 2 (PTGS2), tumor nitric oxide level." (PMID 34959865, 2021). "Importantly, while tumor burden was reduced by more than 5-fold with anti-Grem1 neutralizing antibody treatment, complete eradication of tumor burden was not achieved." (PMID 32756430, 2020). "Interestingly, the tumor suppressor miR-137 could curtail EMT, cell migration and invasion in CC cells via blockade of the TGF-β/smad pathway by binding to GREM1." (PMID 31143092, 2019). "We propose that there may be an association between expression of GREM1 and lack of expression of the estrogen receptor, ESR1, as we only found GREM1 expression among the ESR1 negative tumor cells." (PMID 31694641, 2019). "Addition of TGF-β to tumor cell-N-MSC co-culture augmented MX2, BST2 and IL6 (right columns) but not ADAMTS12, LOXL2 GREM1 or CHI3L1 expression in N-MSCs." (PMID 29503225, 2018). "The expression of GREM1 and COL1A2 could not be detected in LK0824, LK0858, or LK0923 tumor monocultures by qRT-PCR; thus, the Ct-values were set to 40 in order to enable fold-change calculations using the comparative Ct method." (PMID 34283070, 2021). "However, in our samples, the four genes were expressed in T-MSCs, and more modestly in N-MSCs but not (GREM1 and LOXL2) or weakly so (ITGA11 and ADAMTS12) in the tumor cells (data not shown)." (PMID 29503225, 2018).
infection (6 papers, 2018 to 2025). The state of being infected such as from the introduction of a foreign agent such as serum, vaccine, antigenic substance or organism. "Only one gene (GREM1) was unique in response to infection with UT205 and regulated negatively." (PMID 32391286, 2020).
colon polyps (3 papers, 2016 to 2023). "Taken together, those studies suggest that reducing GREM1 mRNA (and thus protein) expression or inhibiting GREM1 function may be a novel therapeutic strategy in intestinal disorders characterised by dysregulated Wnt–BMP signalling or aberrant gremlin 1 expression." (PMID 32297672, 2020).
kidney disease (3 papers, 2021 to 2023). "Experimental gain- and loss-of-function studies targeting Grem-1 in renal cells as well as in murine models of kidney disease have demonstrated the key role of Gremlin-1 in the regulation of inflammation and fibrosis-related processes." (PMID 35215234, 2022). "The de novo GREM1 expression has been described in several human kidney diseases, including RPGN, DKD and transplant rejection." (PMID 35215234, 2022). "In addition, in human DN, the expression level of Grem1 is positively correlated with the renal tubulointerstitial fibrosis score, suggesting that Grem1 has a deleterious effect on human kidney disease." (PMID 37415117, 2023).
adenocarcinoma (2 papers, 2012 to 2020). A common cancer characterized by the presence of malignant glandular cells. "By RNA-seq profiling of cell types from lung tumors, we found that GREM1, high levels of which are associated with worse patient outcomes, is specifically expressed on fibroblasts in the adenocarcinoma microenvironment." (PMID 32381040, 2020). "To better validate the potential interaction, we co-cultured adenocarcinoma cell lines with primary CAFs expressing high or low amounts of GREM1." (PMID 32381040, 2020). "We next sought evidence for a role for GREM1 in cross-talk between fibroblasts and malignant cells by using the LTMI to correlate gene expression levels in malignant cells from adenocarcinoma with the level of GREM1 in fibroblasts from the same tumors." (PMID 32381040, 2020). "Additionally, higher adenocarcinoma fibroblast GREM1 correlated with lower malignant cell glucocorticoid metabolism gene expression." (PMID 32381040, 2020). "To test a positive causal association of GREM1 with malignant cell behavior, we treated adenocarcinoma cell lines with low intrinsic expression of the gene (HCC78 and SW1573) with recombinant GREM1." (PMID 32381040, 2020). "Expression levels of genes involved in translation initiation, ribosomal biogenesis, and invasiveness in malignant cells were positively correlated with GREM1 expression in fibroblasts from the same patient in adenocarcinoma but not in SCC." (PMID 32381040, 2020). "Genes related to cellular transformation and hypoxia were also higher when GREM1 was higher in adenocarcinoma, but not SCC." (PMID 32381040, 2020). "Exogenous GREM1 protein increased the proliferation of adenocarcinoma cell lines, but might be an indirect effect rather than mechanistic." (PMID 32381040, 2020). "Additionally, GREM1 has been shown to bind and activate the vascular endothelial growth factor (VEGF) receptor Kinase Insert Domain Receptor (KDR, also known as VEGFR2, one of two receptors for VEGF), which is expressed in endothelial cells of both adenocarcinoma and SCC." (PMID 32381040, 2020). "To test if GREM1 may have an autocrine function in these cells, we knocked down the transcript in high GREM1 expressing H1755 (which does not express the KDR receptor) and H1792 (which does express KDR) adenocarcinoma cells using siRNA." (PMID 32381040, 2020).
metabolic disorders (2 papers, 2023 to 2026). "This corroborates the previously reported role of GREM1 in adipose tissue dysfunction and metabolic disorders." (PMID 41596576, 2026).
neurological diseases (1 paper, 2021). "In the future, Grem1 may hold value beyond understanding the cellular biology of brain development and function as we develop new approaches to help tackle complex neurodevelopmental and neurological diseases." (PMID 34184027, 2021).
GREM1 also shares sentences with these, for which no sentence is quoted: type 2 diabetes (9 papers); idiopathic pulmonary fibrosis (7); Angelman syndrome (6); epilepsy (6); ovarian cancer (5); lung disease (4); colorectal (3); colorectal polyps (3); non-alcoholic fatty liver disease (3); non-small cell lung carcinoma (3); autism (2); cardiovascular disease (2); clear cell renal carcinoma (2); colon (2); Cowden disease (2); dialysis (2); dilatative cardiomyopathy (2); ductal breast carcinoma in situ (2); dysplasia (2); enteropathy (2); gestational diabetes mellitus (2); heart failure (2); Hepatitis (2); interstitial lung disease (2); malignant mesothelioma (2); Myocardial fibrosis (2); neurodevelopmental disorder (2); oral cavity SCC (2); Peritoneal Fibrosis (2); polycystic ovarian syndrome (2).
A further 90 diseases each share a sentence with GREM1 in 2 papers or fewer.